ZNF733P (zinc finger protein 733, pseudogene)
Synonyms: formerly ZNF733
Gene: Transcribed unprocessed pseudogene on chromosome 7 (63,291,518 to 63,303,988, reverse strand). Ensembl gene ENSG00000185037.
Diseases named in the same sentence as ZNF733P in open-access papers:
ZNF733P is named in the same sentence as 1 disease in open-access papers, as found by Europe PMC text mining. Sharing a sentence is not in itself a finding about the gene and the disease. The quoted sentences say what the papers report.
neurodevelopmental disorder (1 paper, 2025). A behavioral and cognitive disorder with onset during the developmental period that involves impaired or aberrant development of intellectual, motor, or social functions. "ZNF733P, identified from all tissues in males, is a pseudogene located nearby many zinc-finger protein-encoding genes close to the centromere of chromosome 7 and to our knowledge, has not previously been associated with neurodevelopmental disorders." (PMID 40307894, 2025).